HDAC8 (histone deacetylase 8)
Diseases named in the same sentence as HDAC8 in open-access papers (continued):
Sharing a sentence is not in itself a finding about the gene and the disease.
melanoma (19 papers, 2012 to 2025). A malignant, usually aggressive tumor composed of atypical, neoplastic melanocytes. "scRNA-seq data further associated HDAC8 expression with a neural crest stem cell signature in melanoma BrM, underscoring its role in metastasis." (PMID 40016470, 2025). "In fact, the expression of HDAC8 has been reported to be associated with improved survival in patients with melanoma." (PMID 36831463, 2023). "To investigate this, we interrogated the human melanoma scRNA-seq data and found that HDAC8 expression was associated with an OXPHOS gene signature." (PMID 38030596, 2023). "Accordingly, we found that increased expression of HDAC8 in clinical melanoma samples from the TCGA dataset was significantly associated with decreased overall survival." (PMID 38030596, 2023). "HDAC8 expression is associated with improved survival in melanoma, but HDAC1 and HDAC8 also correlate with increase phosphorylated p65—a subunit of the NF-κB complex, which is associated with resistance to MAPK inhibitors." (PMID 26426052, 2015). "Patients with melanoma with high levels of HDAC8 were associated with poor DMFS." (PMID 36831463, 2023). "Similarly, HDAC8 has been implicated in colorectal cancer metastasis and melanoma brain invasion." (PMID 40332124, 2025). "As these data suggested the HDAC8-driven transcriptional program was associated with an invasive, metastatic phenotype we next determined whether increased HDAC8 expression also correlated with previously identified melanoma transcriptional states." (PMID 38030596, 2023). "HDAC8 expression is upregulated in resistant BRAF-mutant melanoma cells, where HDAC8 deacetylates c-Jun to reactivate MAPK signaling." (PMID 39935431, 2025). "The study showed that stress-induced HDAC8 activity leads to a neural crest stem cell-like transcriptional state, enhancing melanoma cell invasion and resistance to stress." (PMID 39200315, 2024). "The study reported that increased HDAC8 activity led to a 50% increase in brain metastasis in a mouse model of melanoma, highlighting the potential of targeting HDAC8 to mitigate melanoma brain metastasis." (PMID 39200315, 2024). "Increased HDAC8 expression led to increased survival of melanoma cells exposed to hypoxia, UV irradiation and after treatment with BRAF-MEKi therapy." (PMID 38030596, 2023). "Induction of this program by HDAC8 leads to the melanoma cells adopting a highly resilient, amoeboid phenotype that drives invasion and survival under both shear stress conditions and in the brain parenchyma." (PMID 38030596, 2023). "Exposure of WM164 and SK-MEL-28 melanoma cells to high levels of fluid shear stress (10 dyne/cm2) over 24 h led to high levels of cell death in the control (EV) cells that were reduced by 80–90% in HDAC8-expressing melanoma cells." (PMID 38030596, 2023). "Our work provides evidence that stress-induced HDAC8 activity regulates an invasive melanoma cell state that increases melanoma brain metastasis development." (PMID 38030596, 2023). "An analysis of a panel of melanoma cell lines identified those with either low or high expression of HDAC8." (PMID 38030596, 2023). "First, the effects of HDAC8 on the amoeboid cell state increased the robustness of the melanoma cells (e.g., the cells are more compact with increased mechanical strength) leading to their increased survival under fluid shear stress conditions." (PMID 38030596, 2023). "Similar HDAC8 responses were also seen in human melanoma cells treated with either UV irradiation of hypoxia." (PMID 38030596, 2023). "We next focused on the propensity for HDAC8 expressing melanoma cells to form melanoma brain metastases." (PMID 38030596, 2023). "Collectively, these results indicate that HDAC8 upregulates both the short- and long-term proliferation of melanoma cells." (PMID 36831463, 2023).
melanoma (continued). "After revealing the crucial role of HDAC8 in regulating HIF-1α along with its tumorigenic function in melanoma in vitro, we analyzed the significance of HDAC8 expression in melanoma patient survival." (PMID 36831463, 2023). "Although studies have elucidated the crucial role of HDAC8 in promoting tumor progression, in melanoma, the tumorigenic role of HDAC8 remains controversial." (PMID 36831463, 2023). "Exposure of melanocytes and melanoma cells to multiple stresses increases HDAC8 activation leading to a neural crest-stem cell transcriptional state and an amoeboid, invasive phenotype that increases seeding to the brain." (PMID 38030596, 2023). "Control or HDAC8 expressing WM164 melanoma cells were injected into the left ventricle of the hearts of mice and organs collected at 5 day intervals to identify potential metastatic sites." (PMID 38030596, 2023). "In the current study we identified a role for HDAC8 in driving a stress-induced transcriptional state in melanoma cells that increases metastasis to the brain." (PMID 38030596, 2023). "Here, we show that HDAC8 is a stress-induced regulator of transcriptional state changes in melanoma cells." (PMID 38030596, 2023). "HDAC8 expression/activity was also increased in melanoma cells following exposure to multiple stresses including UV irradiation, hypoxia, and drug treatment." (PMID 38030596, 2023). "In melanoma, HDAC8 mediates the escape from BRAF inhibitor therapy, and HDAC8 and BRAF dual inhibition has been suggested as a potential therapeutic strategy for melanoma treatment." (PMID 36831463, 2023). "Stable expression of HDAC8 in a BRAFi sensitive melanoma cell line significantly shifted the BRAFi vemurafenib IC50 and inhibited the proliferation rate." (PMID 38030596, 2023). "An RNA-seq analysis of the HDAC8-driven transcriptional state showed the gene expression profile was akin to the melanoma neural crest stem cell (NCSC)-like state." (PMID 38030596, 2023). "Functional studies were then undertaken to determine if inhibition of EP300 (mimicking its deacetylation by HDAC8) would alter sensitivity of melanoma cells to BRAFi therapy." (PMID 38030596, 2023). "Our results, which point to another tumorigenic role of HDAC8 in melanoma, prompted our investigation of HDAC8 in melanoma progression." (PMID 36831463, 2023). "Interrogation of single cell RNA-seq data from a cohort of melanoma brain and leptomeningeal metastasis specimens revealed a correlation between expression of HDAC8 and the NCSC transcriptional signature." (PMID 38030596, 2023). "In patients with melanoma, HDAC8 and HIF1A expressions show a positive correlation and the elevated expression of these genes is associated with poor prognosis." (PMID 36831463, 2023). "Lastly, we corroborated our results with samples from patients with melanoma, which showed that the upregulation of HDAC8 and HIF-1α is correlated with poor prognosis in melanoma." (PMID 36831463, 2023). "Phenotypically, HDAC8 drives the melanoma cells to adopt an amoeboid phenotype that promotes melanoma cell survival under shear stress conditions, enhances invasive capacity and increases the formation of brain metastases." (PMID 38030596, 2023). "Together, these results suggest that HDAC8 promotes cell proliferation and migration while validating the tumorigenic role of HDAC8 in melanoma progression." (PMID 36831463, 2023). "Through inhibitor screening, we identified that HDAC8 effectively regulates HIF-1α in melanoma cells." (PMID 36831463, 2023). "HDAC8 is consistently overexpressed in BRAFi-resistant melanoma cell lines, and ectopic expression of HDAC8 in melanoma cells increases BRAFi tolerance." (PMID 36231123, 2022). "Consistent with the in vitro data, co-targeting BRAF and HDAC8 showed synergistic anti-tumor effects in melanoma mouse models." (PMID 36231123, 2022).
melanoma (continued). "In melanoma and colon cancer cells, HDAC8 induces resistance to MEK1/2 inhibition by activating AKT signaling and promoting cell proliferation in the absence of MEK/ERK activation." (PMID 36231123, 2022). "Among three potential acetylation sites (Lys268, Lys271, and Lys273), HDAC8 deacetylates c-Jun at Lys273 and increases its transcriptional activity in melanoma cells." (PMID 36231123, 2022). "In human melanoma, HDAC8 was also shown to induce a resistance to BRAF inhibition through targeting c-JUN." (PMID 34064422, 2021). "We found decrease in the level of HDAC-8 protein as well as enzyme activity in the chrysin treated melanoma cells (neoplastic)." (PMID 22591439, 2012). "HDAC8 may modulate chromatin dynamics and gene expression in melanoma BrM by altering H3K27ac levels and enhancing accessibility at JUN binding sites through the deacetylation of EP300, effectively inactivating it." (PMID 40016470, 2025). "Additionally, recent findings from Moffitt Cancer Center revealed that the HDAC8-mediated inhibition of EP300 drives a transcriptional state that significantly increases melanoma brain metastasis." (PMID 39200315, 2024). "Additionally, the upregulated HDAC8 promoted the brain metastasis of melanoma by enhancing the accessibility of c-Jun binding motifs." (PMID 39627201, 2024). "In this scenario, HDAC10 may work similarly to HDAC8 which modulates p300 function, and increases H3K27ac and chromatin accessibility at Jun-transcriptional sites in melanoma cells." (PMID 38650694, 2024). "Collectively, these findings suggested that the HDAC8-driven transcriptional program could increase invasion of melanoma cells in vivo." (PMID 38030596, 2023). "First, we evaluated whether the pharmacological inhibition of HDAC8 would negatively affect the proliferation of melanoma cells." (PMID 36831463, 2023). "Likewise, introduction of HDAC8 into melanoma cell lines with low endogenous HDAC8 expression increased phospho-Jun and EGFR levels." (PMID 38030596, 2023). "Importantly, targeting HDAC8 showed anti-cancer effects, such as suppressed cell proliferation and migration in melanoma." (PMID 36831463, 2023). "This HDAC8-driven program was also observed in melanocytes exposed to UV irradiation, providing a link between a conserved melanocyte survival program and the aggressive metastatic behavior of melanoma cells." (PMID 38030596, 2023). "Moreover, we verified that HDAC8 promotes the progression of melanoma by enhancing cell proliferation and metastasis." (PMID 36831463, 2023). "We began by determining if HDAC8 was an epigenetic driver of cell state changes in melanoma." (PMID 38030596, 2023). "In addition to this, inhibition of EP300 also mimicked HDAC8 activation by promoting melanoma cell invasion and by increasing the formation of brain metastases in mice." (PMID 38030596, 2023). "Next, we tested whether HDAC8 depletion or inhibition would suppress the metastatic potential of melanoma." (PMID 36831463, 2023). "As the brain is a highly protected, difficult to penetrate organ, surrounded by the blood-brain-barrier, it seems likely that melanoma cells with a high invasive capacity (such as those expressing HDAC8) would have a significant advantage in seeding to the brain." (PMID 38030596, 2023). "As HDAC8 activity also increased in response to other stresses, we reasoned that increased HDAC8 activity could be critical for melanoma transcriptional state switching." (PMID 38030596, 2023). "Increases in both HDAC8 and phospho-c-Jun protein levels were also seen in melanocytes treated with UV irradiation, suggesting a conserved mechanism of stress tolerance between melanocytes and melanoma cells." (PMID 38030596, 2023). "The inhibition of HDAC8 suppresses the proliferation and metastasis of melanoma cells." (PMID 36831463, 2023). "Here, we identify stress-induced HDAC8 activity as driving melanoma brain metastasis development." (PMID 38030596, 2023).
melanoma (continued). "Moreover, HIF1A expression was positively correlated with HDAC8 expression in the samples from patients with melanoma." (PMID 36831463, 2023). "We have demonstrated that stress-mediated activation of HDAC8 leads to a switch from MITF- to Jun-driven transcriptional programs in melanoma cells that leads to the adoption of a transcriptional state with characteristics of the previously reported NCSC state." (PMID 38030596, 2023). "HDAC8 inhibition upregulates HOXA5/STAT3-mediated transcriptional activation of PD-L1 encoding gene, CD274, thereby enhancing anti-tumor T-cell response in melanoma cells." (PMID 36231123, 2022). "HDAC8 mediates BRAF inhibitor (BRAFi) resistance in melanoma cells." (PMID 36231123, 2022). "Moreover, HDAC8 suppresses anti-tumor immunity in melanoma cells by reducing the expression of PD-L1." (PMID 36231123, 2022). "However, various studies have identified the nuclear and cytoplasmic distribution of HDAC8 and predominant cytoplasmic localization in smooth muscle, brain, and melanoma cells." (PMID 36231123, 2022). "HDAC8 was also shown to mediate the resistance to RAF inhibitors in melanoma." (PMID 34064422, 2021). "Moreover, the transcriptional complex composed with HDAC8, HOXA5, and STAT3 controls the transcriptional activation of PD-L1, and the inhibition of HDAC8 can upregulate PD-L1 expression by increasing its activity in melanoma cells." (PMID 34365463, 2021). "However, a recent study showed that multiple stress exposure on melanomas such as BRAFi and MEKi combination, increased HDAC8 expression and lead to a drug-resistant phenotype 60." (PMID 32042336, 2020). "Notably, increased levels of HDAC8 in the cytoplasm of patients with metastatic BRAF-mutant melanoma were correlated with better survival, and the HDAC8 localization within tumor cells seems to be important for its biological effects, either positive or negative, on the cancer patient." (PMID 39935431, 2025). "Targeting HDAC8 could, therefore, be a viable strategy to mitigate melanoma brain metastasis." (PMID 39200315, 2024). "Consequently, the depletion of HDAC8 suppresses cell proliferation and migration in melanoma." (PMID 36831463, 2023). "HDAC8 deacetylates EP300, a histone acetyltransferase, leading to its inactivation and increased melanoma cell invasion." (PMID 39200315, 2024). "In melanoma, PD-L1 seems to be directly controlled primarily by class I HDACs (HDAC1, HDAC2, HDAC3, HDAC8)." (PMID 38672128, 2024). "To determine if this was a conserved response between melanocytes and melanoma cells, we treated 2 primary human melanocyte cell lines (FOM173 and NHEM) with UV irradiation and noted increased expression of HDAC8 and increased phosphorylated c-Jun expression." (PMID 38030596, 2023). "The Transwell assay and wound-healing assay results revealed that HDAC8 KO and PCI-34051 treatment greatly suppress the migration ability of melanoma cells." (PMID 36831463, 2023). "These analyses showed a significant correlation between HDAC8 expression and the NCSC-like gene expression profile in the human melanoma cells." (PMID 38030596, 2023). "Similar to the PCI-34051 results, the genetic ablation of HDAC8 greatly reduced HIF-1α levels under both normoxic and hypoxic conditions in melanoma cells." (PMID 36831463, 2023). "In this study, we delineated an epigenetic mechanism in which the epigenetic eraser HDAC8 stabilizes HIF-1α expression and promotes melanoma progression." (PMID 36831463, 2023). "Following intracardiac injection, HDAC8 expressing SK-MEL-28, WM164 and 1205Lu melanoma cells resulted in significantly more brain metastases compared to the control (EV) cells." (PMID 38030596, 2023). "Collectively, these findings reveal HDAC8 as a novel epigenetic modulator of HIF-1α and present a novel therapeutic strategy in treating patients with melanoma." (PMID 36831463, 2023). "Compared to primary melanoma, the expression levels of HIF1A and HDAC8 were significantly elevated in metastatic melanoma." (PMID 36831463, 2023).
melanoma (continued). "RNA-seq analyses were performed on two melanoma cell lines (WM164 and SK-MEL-28) to determine how upregulation of HDAC8 reshaped the transcriptional landscape." (PMID 38030596, 2023). "In this study, we show that HDAC8 is an epigenetic regulator of HIF-1α, a critical transcription factor that drives tumor progression in various cancers, including melanoma." (PMID 36831463, 2023). "As the HDAC8 expressing cells are highly invasive, we next examined if modulating EP300 expression would alter the invasive capacity of melanoma cells." (PMID 38030596, 2023). "Collectively, the patient survival analysis supports our findings that HDAC8 enhances the expression of HIF-1α and promotes tumor progression in melanoma." (PMID 36831463, 2023). "We found that HDAC8 was required for a resistance to LT and the MEK1/2 inhibitor U0126 in the human colorectal tumor cell line HT-29 and murine melanoma B16-BL6 cells." (PMID 34064422, 2021). "It is possible that HDAC8 induces PLCB1 through deacetylating/activating c-JUN, as in the BRAF inhibitor-resistant melanoma." (PMID 34064422, 2021). "Independent from vemurafenib resistance, the curcumin-harmine-isovanillin combination drug GZ17-6.02 upregulated class I MHCA and suppressed PD-L1 in PDX BRAFV600E melanoma cells, which was mediated by the downregulation of several HDACs (HDAC3, HDAC5, HDAC6, HDAC7, and HDAC8)." (PMID 39935431, 2025). "Therefore, we suggest HDAC8 as a novel regulator of HIF-1α and a therapeutic target for melanoma treatment." (PMID 36831463, 2023). "Here, we demonstrate that a selective-HDAC8 inhibitor functions as an indirect inhibitor of HIF-1α and may be an effective therapeutic strategy in treating not only melanoma but also other solid tumors." (PMID 36831463, 2023). "Furthermore, HDAC8 is correlated with HIF1A expression and poor prognosis in samples from patients with melanoma." (PMID 36831463, 2023). "The HDAC8 promotes the expression of HIF-1α target genes, such as hexokinase 2 (HK2) and glucose transporter protein 1 (GLUT1), by upregulating HIF-1α expression levels and elevating HIF-1α transcriptional activity, which can promote the proliferation and metastasis of melanoma cells." (PMID 39876842, 2024). "Therefore, HDAC8-selective inhibitors may function as indirect HIF-1α inhibitors and may be a promising strategy in treating patients with melanoma." (PMID 36831463, 2023). "However, HDAC8 had nearly no expression in melanoma cells but was expressed in normal skin tissue." (PMID 26747087, 2016).